WTAP (WT1 associated protein)
Diseases named in the same sentence as WTAP in open-access papers (continued):
Sharing a sentence is not in itself a finding about the gene and the disease.
myeloid leukemia (2 papers, 2018 to 2022). A clonal proliferation of myeloid cells and their precursors in the bone marrow, peripheral blood, and spleen. "Subsequently, methyltransferase-like 3 (METTL3), methyltransferase-like 14 (METTL14), Wilm’s tumor 1-associated protein (WTAP), and AlkB homolog 5 (ALKBH5) were reported to be related to myeloid leukemia." (PMID 35720276, 2022).
osteoarthritis (2 papers, 2023 to 2024). A noninflammatory degenerative joint disease occurring chiefly in older persons, characterized by degeneration of the articular cartilage, hypertrophy of bone at the margins and changes in the synovial membrane. "The study was design to investigate the functional roles of Wilms tumor 1-associated protein (WTAP), an enzyme catalyzes m6A modification, in the pathogenesis of osteoarthritis (OA) and further elucidate its possible regulatory mechanism." (PMID 37563688, 2023).
renal carcinoma (2 papers, 2021 to 2022). A carcinoma arising from the epithelium of the renal parenchyma or the renal pelvis. "In summary, WTAP and IGF2BPs are overexpressed in renal cancer, which correlates with a worse prognosis of RCC patients." (PMID 34326314, 2021). "In renal cancer, miR-501-3p upregulates WTAP expression by targeting binding to WTAP." (PMID 36139062, 2022).
adenoma (1 paper, 2022). A neoplasm arising from the epithelium. "M6A modification is regulated by RNA methyltransferase and demethylase, hence we assessed the expression of methyltransferase (METTL3, METTL14 and WTAP) and demethylase (FTO and ALKBH5) in both adenoma and CRC." (PMID 35012593, 2022).
brain tumour (1 paper, 2023). "Again, there are several conflicting reports of m6A regulator expression levels among the different brain tumour entities and non-tumour brain tissue, including ALKBH5, WTAP, METTL14, and YTHDC2." (PMID 36831575, 2023).
cerebellar ataxia (1 paper, 2022). A neurological syndrome characterized by clumsy and uncoordinated movement of the limbs, trunk, and cranial muscles. "Furthermore, WTAP has been found to be closely related with cerebellar development in mice, and WTAP deletion leads to Purkinje cell degeneration, cerebellar ataxia, and cerebellar atrophy." (PMID 36118889, 2022).
cervical squamous cell carcinoma (1 paper, 2022). A squamous cell carcinoma arising from the cervical epithelium. "The results showed that the expressions of WTAP were downregulated; and the expressions of four m6A-RMRs such as HNRNPA2B1, IGF2BP2, FMR1, and HNRNPC were upregulated in patients with preinvasive and invasive cervical squamous cell carcinomas compared with normal controls." (PMID 35211628, 2022).
colorectal adenoma (1 paper, 2022). An adenoma that arises from the colon or rectum. "Our findings revealed significantly upregulated WTAP expression in CRC tissue compared with colorectal adenoma and normal colorectal tissue, indicating that WTAP may be involved in the occurrence of CRC." (PMID 35143566, 2022).
coronary artery disease (1 paper, 2025). "Clinical significance and correlation study of methyltransferase Wilms' tumour 1-associated protein (WTAP) and lipoprotein-associated phospholipase A2 (Lp-PLA2) in patients with coronary artery disease (CAD)." (PMID 41425989, 2025).
depression (1 paper, 2023). "The present study suggested that the m6A-modifying enzyme METTL3, as well as WTAP, may play a key role in the pathogenesis and treatment of depression, which provided some hints for the development of new antidepressant drugs at the epitranscriptomic level." (PMID 37175269, 2023). "Considering that METTL3, METTL14, and WTAP are core components of the methyltransferase complex, and FTO and ALKBH5 are major demethylases, it was reported that METTL3, FTO, and ALKBH5 were implicated in the pathology of depression." (PMID 37175269, 2023). "This suggests that METTL3 and WTAP-mediated changes in m6A modifications may be a potential mechanism for the pathogenesis of depression and the efficacy of antidepressants, and that the neurotrophin signaling pathway plays a key role in this process." (PMID 37175269, 2023). "In conclusion, our study found that hypericin improved depression-like behaviors in UCMS mice, while upregulating METTL3 and WTAP expression in the hippocampi of UCMS mice and modifying the neurotrophin signaling pathway through m6A modification to exhibit antidepressant effects." (PMID 37175269, 2023).
diabetic foot ulcer (1 paper, 2025). "The Wilms tumor 1-associated protein (WTAP)-DNA methyltransferase 1 (DNMT1) axis acts as a pivotal regulator of diabetic foot ulcer healing." (PMID 40943661, 2025).
epilepsy (1 paper, 2022). A brain disorder characterized by episodes of abnormally increased neuronal discharge resulting in transient episodes of sensory or motor neurological dysfunction, or psychic dysfunction. "The qRT-PCR results indicated that WTAP and YTHDC1 have higher expression levels in patients with epilepsy, while HNRNPC was expressed to a lower level, which is consistent with our integrated analysis." (PMID 36468034, 2022). "Firstly, we analyzed the expression of 17 m6A-related genes extracted from a public dataset and found that seven of them (HNRNPC, WTAP, RBM15, YTHDC1, YTHDC2, CBLL1, and RBMX) were differentially expressed between patients with epilepsy and healthy individuals." (PMID 36468034, 2022).
Hepatitis (1 paper, 2025). Inflammation of the liver. "In contrast, other m6A regulators, including METTL3, METTL14, WTAP, FTO, ALKBH5, YTHDC1, and YTHDC2, exhibited different protein expression patterns during ConA-induced hepatitis." (PMID 40092485, 2025).
keloid (1 paper, 2022). An irregularly shaped, elevated mark on the skin caused by deposits of excessive amounts of collagen during wound healing. "The Western blotting results showed that the proteins of METTL3 and WTAP in keloid were significantly higher than those in normal skin (p < 0.05)." (PMID 36263010, 2022).
kidney cancer (1 paper, 2021). Primary or metastatic malignant neoplasm involving the kidney. "Similarly, WTAP and IGF2BPs were higher in kidney cancer tissues than in adjacent normal controls." (PMID 34326314, 2021).
liver steatosis (1 paper, 2025). "Collectively, these data suggest that the WTAP/GLUT3 axis plays a role in promoting H. pylori-induced liver steatosis, partly through the activation of glycolysis." (PMID 41384837, 2025).
male infertility (1 paper, 2026). The inability of the male to effect fertilization of an ovum after a specified period of unprotected intercourse. "Conditional knockout of WTAP, specifically in Sertoli cells, induces male infertility accompanied by severe dysregulation of alternative splicing in spermatogonial stem cells, establishing the indispensable role of WTAP in maintaining the spermatogonial stem cell niche." (PMID 41546098, 2026).
metastatic melanoma (1 paper, 2022). A melanoma that has spread from its primary site to another anatomic site. "In anti-PD-1 immunotherapy cohort (GSE78220; Patients with metastatic melanoma treated with anti-PD-1 antibody immunotherapy), patients with a high expression of WTAP exhibited a survival benefit trend." (PMID 35155433, 2022).
Nephropathy (1 paper, 2025). A nonspecific term referring to disease or damage of the kidneys. "We then detected the mRNA expression of m6A methyltransferases (METTL3, METTL14, and WTAP) and demethyltransferases (FTO and ALKBH5) and found that METTL3 and FTO mRNA expression was upregulated in Pb-induced nephropathy compared with controls." (PMID 40520008, 2025).
oncocytoma (1 paper, 2021). "Compared to normal renal tissue protein expression of all investigated methyltransferases was increased in oncocytoma (METTL3 P < .001, METTL4 P < 0,001, METTL14 P = .003, KIAA1429 P = .001, WTAP P = .001)." (PMID 35474700, 2021).
osteoporosis (1 paper, 2023). A condition of reduced bone mass, with decreased cortical thickness and a decrease in the number and size of the trabeculae of cancellous bone (but normal chemical composition), resulting in increased fracture incidence. "Our results demonstrated that the WTAP/YTHDC1/miR-181a and miR-181c/SFRP1 axis regulated the differentiation fate of BMSCs, suggesting that it might be a potential therapeutic target for osteoporosis." (PMID 36650131, 2023).
ovarian endometriosis (1 paper, 2023). A non-neoplastic disorder characterized by the growth of endometrial tissue in the ovaries. "Altogether, these findings suggest that the upregulation of WTAP in ovarian endometriosis might function as a protective effect." (PMID 37900186, 2023).
preeclampsia (1 paper, 2025). Preeclampsia is a hypertensive disorder of pregnancy that is characterized by new-onset hypertension with proteinuria presenting after 20 weeks of gestation, and depending on mild or severe forms may initially present with severe headache, visual disturbances, and hyperreflexia. "Overall, this study identifies WTAP as a key regulator of placental ferroptosis and establishes the WTAP–YTHDF2–NCOA4 pathway as a potential therapeutic target for preeclampsia." (PMID 41257944, 2025).
prostate adenocarcinoma (1 paper, 2022). "A comparative analysis of genetic alterations in METTL3, METTL14, WTAP and CBLL1 in primary prostate adenocarcinoma and metastatic PCa patients was undertaken." (PMID 36733939, 2022). "Analysis of publicly available PCa patient datasets identified that METTL3 and WTAP expression was higher in primary prostate adenocarcinoma than in non-malignant prostate tissue, whereas conversely, METTL14 expression was found to be significantly lower." (PMID 36733939, 2022). "It was found that METTL3 (p < .0001) and WTAP (p < .01) expression were significantly higher in primary prostate adenocarcinoma patient samples compared with non-malignant prostate tissue, whereas METTL14 expression was significantly lower (p < .01) in tumour compared with non-malignant tissue." (PMID 36733939, 2022). "Expression and sub-cellular localisation of METTL3, METTL14, WTAP and CBLL1 were confirmed using IHC in both non-malignant and primary prostate adenocarcinoma specimens." (PMID 36733939, 2022).
pulmonary arterial hypertension (1 paper, 2024). Pulmonary arterial hypertension (PAH) is a group of diseases characterized by mean pulmonary artery pressure >20 mmHg and elevated pulmonary arterial resistance leading to right heart failure. "Moreover, bioinformatics analysis revealed that in MCT-PAH rats, there was an upregulation of METTL3, WTAP, and YTHDF1, and the eIF2α mRNA with common sequences of m6A modification was also upregulated, thereby promoting the occurrence and development of pulmonary arterial hypertension." (PMID 39155349, 2024).
skin aging (1 paper, 2024). The gradual irreversible changes in structure of skin that occur as a result of the passage of time.. "In the current study, we found the up-regulation of WTAP in aging skin tissues and senescent HDFs, overexpressed WTAP induced HDFs and skin aging." (PMID 38481803, 2024).
squamous cell carcinoma (1 paper, 2021). A carcinoma arising from squamous epithelial cells. "In addition, we found only WTAP and HNRNPC were up-regulated in squamous cell carcinoma compared to adenocarcinoma." (PMID 33748145, 2021).
steatosis (1 paper, 2025). Increased lipid within the cytoplasm of cells. "The “second hit,” which may involve factors such as H. pylori infection, WTAP upregulation, oxidative stress, and inflammatory cytokines, is necessary to precipitate the clinical manifestations of steatosis, inflammation, and fibrosis." (PMID 41384837, 2025).
tumor (135 papers, 2017 to 2026). "AC115619-22aa reduced overall m6A levels and inhibited tumor growth by binding to Wilms tumor 1-associated protein (WTAP) and hindering the assembly of the m6A methyltransferase complex." (PMID 41291707, 2025). "The binding partner to the WT1 protein, Wilms’ tumor 1-associating protein (WTAP), has been suggested to have an oncogenic role in many tumor types." (PMID 38173713, 2023). "As for NSCLC, previous studies also showed that miR-433-3p targeted WT1 associated protein (WTAP) to reduced tumor cell proliferation and migration." (PMID 33593390, 2021). "Three important subunits of the m6A methyltransferase complex, methyltransferase-like 3 (METTL3), METTL14, and WT1 associated protein (WTAP), were found different expression in tumor tissues." (PMID 34178650, 2021). "Furthermore, WTAP was upregulated in NSCLC and mediated m6A modification of circSMOC1 and circSMOC1 abolished WTAP knockdown‐caused tumour‐suppressive effects." (PMID 39632285, 2024). "Besides, the overexpression of WTAP was associated with tumor size, metastasis, and TNM stage." (PMID 32814762, 2020). "Subsequent analysis showed that WTAP expression was related to tumor grade and nodal metastasis status, suggesting that WTAP acts as an oncogene in HCC." (PMID 40846737, 2025). "Firstly, it was found that the expression of WTAP, as one of m6A methyltransferase, dramatically decreased in tumor tissues compared to normal tissue." (PMID 39744575, 2025). "Several studies have highlighted the pivotal role of WTAP-mediated m6A modifications in regulating tumor proliferation, invasion, and apoptosis." (PMID 40707002, 2025). "In recent years, WTAP has been identified as having a significant oncogenic role, particularly in HCC, where it is closely linked to the formation of the tumor immune microenvironment and the response to immunotherapy." (PMID 39911396, 2025). "Overexpression of WTAP can counteract the tumor suppressive effect of miR-455-3p in PCa cells, thereby promoting PCa progression." (PMID 41256854, 2025). "Reducing the expression levels of METTL14 and WTAP has limited effects on the tumour development and behaviour of endometrioid epithelial OC cells cultured in vitro." (PMID 40356909, 2025). "Specifically, we identified KLF9, a known tumor suppressor, as a potential downstream effector of WTAP." (PMID 41301778, 2025). "Current research on methyltransferases, particularly METTL3, METTL14, and WTAP, primarily focuses on their roles in regulating ferroptosis and tumor growth." (PMID 40271153, 2025). "In acute myeloid leukaemia, WTAP has been shown to be up-regulated at its expression level and plays an important role in the proliferation and differentiation of tumours." (PMID 40356909, 2025). "Based on its multiple functions and its close relationship with the cyclical activity, metabolism and autophagy of tumor cells, WTAP has great potential in clinical cancer treatment and prognosis." (PMID 41256854, 2025). "Functional assays revealed that knockdown of WTAP repressed the colony formation and cell invasion abilities and circSMOC1 abolished WTAP knockdown‐induced tumour‐suppressive effects in A549 and 95D cells." (PMID 39632285, 2024). "At present, WTAP has mostly been demonstrated to be involved in cell cycle regulation, X chromosome inactivation, tumor development and alternative splicing." (PMID 37563688, 2023). "Recently, the mechanism of METTL14 and WTAP methylation effects on tumour proliferation through the PI3K-AKT pathways in RCC has been demonstrated." (PMID 37284313, 2023). "Among the three major components of the writer complex, only METTL3 was upregulated in LUAD as determined by ELISA; METTL14 and WTAP were expressed at similar levels in adjacent and tumor tissues." (PMID 35078505, 2022).
tumor (continued). "Our study included 375 CRC tissue samples and found that WTAP protein expression negatively correlated with differentiation of the tumor, and that WTAP protein expression is lowest in poorly differentiated tumors." (PMID 35143566, 2022). "Several studies have demonstrated that m6A modulators (e.g., METTL3 and WTAP) affect tumor glucose metabolism by regulating glycolytic enzymes (Warburg effect) to promote proliferation." (PMID 35794625, 2022). "Overall, these results showed that the expression of METTL3, METTL14, and WTAP were higher in tumor samples than in the adjacent normal samples." (PMID 35778697, 2022). "Previous studies showed that the expression of m6A writers (METTL3, RBM15, WTAP), eraser (FTO, ALKBH5) and reader (YTHDF3, YTHDC2) was associated with pathological stage, tumor stage, andprognosis of patients with GC." (PMID 35977935, 2022). "The silencing of the WATP gene significantly inhibited the proliferation and migration of tumor cell lines, which further confirmed the important role of WTAP in the tumorigenesis and progression of HCC." (PMID 35480109, 2022). "Mechanistically, CA4 interacts directly with WTAP, and the tumor suppressor function of CA4 is dependent on WTAP modification." (PMID 36139062, 2022). "Ji and colleagues reported that WTAP expression was significantly higher in PCa and that lower WTAP expression was associated with elevated Gleason score, suggesting complex roles for WTAP in tumour initiation and progression." (PMID 36733939, 2022). "High WTAP expression in patients with OS has been associated with tumor size, metastasis and TNM stage, and overexpression of WTAP has been correlated with poor prognosis." (PMID 35436972, 2022). "As the classical complex of “writers”, WTAP has been recently shown to promote tumor progression in an m6A-dependent manner." (PMID 35480109, 2022). "Multiple m6A methylation regulators have been shown to be associated with prognosis of different tumor types, including METTL3, WTAP, IGF2BP, FTO, and YTHDF." (PMID 35794625, 2022). "The expression of WTAP was negatively correlated with tumor purity, but positively correlated with CD8 + T cells, CD4 + T cells, neutrophils, and dendritic cells." (PMID 35148766, 2022). "Analysis of TCGA data in TIMER revealed that compared with normal tissues, the expression level of WTAP in tumor tissues vary in different cancers." (PMID 36171885, 2022). "Although METTL3, METTL14 and WTAP can form RNA methyltransferase complexes, which regulate the fate of tumour development, studies have shown that METTL3 and METTL14 also have independent regulatory functions in regulating transcription." (PMID 36434140, 2022). "The association between WTAP expression and prognosis in patients with CRC varied from separate microarray databases 52,53, suggesting the multidimensional function of WTAP in tumor progression." (PMID 33456561, 2021). "Recent studies have revealed m6A methylation components can act as tumor-associated factors, including “writers” (METTL3/14, WTAP and KIAA1429), “erasers” (FTO and ALKBH5), and “readers” (YTHDF1/2/3, HNRNPA2B1, BCDIN3D)." (PMID 33791305, 2021). "The infiltration of tumor-associated T cells in the TME was associated with high levels of m6A modification, which was mediated by WTAP mRNA expression." (PMID 34956201, 2021). "Except for KIAA1429, YTHDC1 and WTAP, the remaining 10 m6A methylation regulators were differentially expressed between normal and tumor tissue." (PMID 33995635, 2021). "Growing evidence has demonstrated that m6A modification is closely associated with tumorigenesis, tumor differentiation, tumor proliferation, tumor invasion and worse survival in BC patients, including METTL3, METTL14, WTAP, ALKBH5, IGF2BP2, IGF2BP3, and FTO." (PMID 33926554, 2021). "Consistently, the protein levels of WTAP in tumor tissues also demonstrated a similar pattern as its mRNA levels." (PMID 34081626, 2021).